CARD9 (caspase recruitment domain family member 9)
Diseases named in the same sentence as CARD9 in open-access papers (continued):
Sharing a sentence is not in itself a finding about the gene and the disease.
atherosclerosis (continued). "Higher production of IL-1β might be involved, at least in part, in the acceleration of atherosclerosis in Apoe-/-Card9-/- mice and might be due to increased CD36 expression." (PMID 37528097, 2023). "In this scope, future studies should determine whether CARD9 deletion reduces macrophage infiltration and atherosclerosis development under hyperglycaemic conditions." (PMID 30867470, 2019). "In the context of atherosclerosis, other mechanisms, including autophagy, could account for enhanced apoptosis susceptibility of macrophages in the absence of Card9." (PMID 37528097, 2023). "However, our findings of increased atherosclerosis in immune-deficient Apoe-/-Rag2-/-Card9-/- mice ruled out the possibility that the acceleration of atherosclerosis in the absence of Card9 was mediated by a modulation of the adaptive immune system." (PMID 37528097, 2023). "However, CARD9 signaling is very complex, and there are apparent inconsistencies in the roles of CARD9 signaling in the same pathological conditions including cardiac ischemia/reperfusion (I/R) injury and atherosclerosis for largely undefined mechanism(s)." (PMID 35432375, 2022). "Hence, we hypothesize that activation of Dectin-2 and CARD9 aggravate inflammation and thereby enhance atherosclerosis development." (PMID 30867470, 2019). "Recent studies have demonstrated that CARD9 is crucial in the development and progression of various cardiovascular diseases, including TAC‐induced HF, myocardial ischemia/reperfusion, hypertension and atherosclerosis." (PMID 39118286, 2024). "However, deletion of hematopoietic CARD9 shows no protective effects on atherosclerosis, probably because of no significant reduction of cytokines secretion (IL-6 and TNF-α) or mRNA expressions (IL-1β, IL-10, TNF-α, and MCP-1)." (PMID 35432375, 2022). "The acceleration of atherosclerosis, which is known to be an inflammatory disease, in the absence of Card9 might be counterintuitive since Card9 is a downstream adapter of fungal- and bacteria-induced activation of TLRs, as well as activation of ITAM-containing non-TLRs and Dectin-135,36." (PMID 37528097, 2023). "However, deletion of hematopoietic CARD9 did not exhibit a protective effect in atherosclerosis." (PMID 35173530, 2022).
colorectal cancer (6 papers, 2019 to 2024). A primary or metastatic malignant neoplasm that affects the colon or rectum. "Treatment of CARD9 deficient tumor-bearing mice with an anti-fungal fluconazole suppressed tumor growth in the colorectal cancer mouse model." (PMID 32509781, 2020). "Recent evidence suggests that CARD9 deficiency impaired macrophage fungicidal functions which led to increased fungal loads and a notable increase in Candida tropicalis in a colorectal cancer mouse model." (PMID 32509781, 2020). "The crucial role of CARD9 in intestinal immune homeostasis is also highlighted by the impact of CARD9 signaling on the development of colorectal cancer." (PMID 36553655, 2022). "However, our previous study indicated Card9 (the downstream adaptor protein of Dectin3) reduced the incidence of colorectal cancer by inhibiting MDSCs recruitment." (PMID 34480018, 2021). "These experiments indicate that CARD9 signaling in the immune environment of developing colorectal cancers can trigger the tumor-promoting STAT3 pathway within tumor cells, presumably via ILC-mediated IL-22 production, comparable to its role during epithelial regeneration after acute colitis." (PMID 30906296, 2019).
cryptococcosis (6 papers, 2018 to 2025). An acute or chronic, localized or disseminated infection by Cryptococcus neoformans. "To examine the effect of CARD9 deficiency on the clinical course of cryptococcal infection, we intratracheally infected WT and CARD9-deficient mice with different Cryptococcus strains." (PMID 30131805, 2018). "While this gene is yet to be validated in koalas, the phenotype of CARD9 mutations in humans and mice, together with its role in fungal immunity, highlight it as an ideal candidate for exploration of host-related susceptibility to cryptococcosis in the koala." (PMID 38921395, 2024). "In CARD9 KO mice, the discrepancy between macrophage accumulation and chemokine levels has been reported in a cryptococcal infection model, but the reason for this inconsistency was unclear." (PMID 40574842, 2025). "Accordingly, it will be of interest to investigate the precise immune defects that are regulated by Card9 in the brain in response to disseminated cryptococcal infection and to compare these to experimental cerebral candidiasis." (PMID 38921420, 2024). "Card9 is mainly expressed by cells of the myeloid lineage; accordingly, recruitment of these cells was analyzed at serial time points after cryptococcal infection." (PMID 38921420, 2024). "Taken together, these findings strongly suggest that Card9 regulates various aspects of host immunity against pulmonary cryptococcal infection such as lung macrophage polarization." (PMID 38921420, 2024). "We advocate for further investigations into the role of CARD9 in cryptococcal infection and highlight several other avenues for ongoing research." (PMID 38921395, 2024). "In this study, we have extensively characterized the role of Dectin-3 and CARD9 during pulmonary cryptococcosis using an experimental murine model of pulmonary infection with C. neoformans and C. gattii." (PMID 30131805, 2018). "Consequently, we endeavored to utilize LW10 within an experimental murine model of cryptococcosis to determine the role of CARD9 in mediating protection against pulmonary C. neoformans infections." (PMID 31911495, 2020). "However, the impact of CARD9 on neutrophils recruitment and function against cryptococcal infection seems to be complicated depending on different serotypes of Cryptococcus infection." (PMID 30131805, 2018).
primary immunodeficiency (6 papers, 2013 to 2026). "Examples of primary immunodeficiencies, which are associated with CMC, are autosomal dominant hyper IgE syndrome (HIES, STAT3 deficiency), caspase recruitment domain family member 9 (CARD9) deficiency, and dectin-1 deficiency." (PMID 37623553, 2023). "CARD9 mutation is one of the important causes of primary immunodeficiency disease.There have been no reports of TM infection patients with CARD9 mutations in children." (PMID 34234782, 2021).
tuberculosis (6 papers, 2011 to 2025). A chronic, recurrent infection caused by the bacterium Mycobacterium tuberculosis. "Previous researches have demonstrated that CARD9 was associated with some inflammatory diseases such as tuberculosis, IBD, CD and rheumatoid arthritis." (PMID 29100328, 2017). "Tuberculosis (TB), a chronic infectious disease affecting the lung, is lethal in Card9-deficient mice." (PMID 27684065, 2016). "The recent work identifying Mincle as a TDM receptor provides a molecular basis for the immunostimulatory activity of TDM and identifies the Mincle-FcRy-Syk-CARD9 pathway as a target for vaccine development against tuberculosis." (PMID 21334257, 2011). "Studies in this area have demonstrated that TDM and TDB selectively activate the FcRγ-Syk-CARD9 pathway to induce protective Th1 and Th17 immunity after subunit vaccination against tuberculosis in mice." (PMID 21334257, 2011). "The Dectin-1-Syk-CARD9 signaling pathway plays an important role in tuberculosis immunity." (PMID 41041311, 2025). "In experimental animals CARD9 protects against infection with the opportunistic fungus Candida albicans and intracellular bacteria, such as Listeria monocytogenes, and is essential for control of tuberculosis (TB)." (PMID 27684065, 2016). "Vaccine adjuvants bind to PRRs to trigger robust Th17 and Th1 responses through CARD9-medated signaling pathway, a promising protective mechanism against several infections including tuberculosis (TB), chlamydial infection or malaria in preclinical studies." (PMID 35432375, 2022).
Arthritis (5 papers, 2016 to 2023). Inflammation of a joint. "As a result, Card9−/− animals are protected from autoantibody-induced arthritis, and this protection was mapped to neutrophils using neutrophil-specific Card9-deficient mice." (PMID 30127791, 2018). "The caspase recruitment domain family member 9 gene (CARD9) which encodes an adaptor protein that integrates signals downstream of pattern recognition receptors, has been shown to be important in mouse models of arthritis." (PMID 30850234, 2019). "Genetic deficiency of CARD9 suppresses autoantibody-induced arthritis and dermatitis in mice." (PMID 27032818, 2016). "Different from the previously published paper on CARD9 deficiency in macrophages, myeloid, and dendritic cells, CARD9–deficiency neutrophils may greatly impair neutrophil functions, leading to fungal brain infection, arthritis, and dermatitis." (PMID 33488294, 2021). "CARD9 knockdown effectively alleviated autoantibody-induced arthritis and dermatitis in a mouse model." (PMID 33488294, 2021). "Clinical signs of arthritis were quantified in CARD9 knockout mice which showed significant ankle thickening (P = 0.0047) and reduced grip strength (P = 2 × 10−4), compared to wild-type mice." (PMID 30850234, 2019). "The normal LTB4 release also likely explains why Card9−/− animals are only partially protected from arthritis and dermatitis development." (PMID 27032818, 2016). "Taken together, the defective arthritis and dermatitis development in Card9−/− mice is mostly due to the role of CARD9 within the neutrophil compartment." (PMID 27032818, 2016). "To test the role of CARD9 in non-infectious inflammation, we tested the effect of CARD9 deficiency on autoantibody-induced arthritis development in the K/B × N serum-transfer model." (PMID 27032818, 2016). "Card9−/− mice showed substantially reduced signs of arthritis development." (PMID 27032818, 2016). "Similarly, Card9−/− (EUCOMM) mice were also strongly protected from visible signs of arthritis (P=6.6 × 10−4; two-way ANOVA) and ankle thickening (P=0.0038; two-way ANOVA)." (PMID 27032818, 2016). "Therefore, CARD9 plays a major role in the development of autoantibody-induced arthritis." (PMID 27032818, 2016). "Similar to intact mice, Card9−/− bone marrow chimeras also showed partial protection from arthritis development in the K/B × N serum-transfer model (P values between 9.1 × 10−11 and 1.6 × 10−4; two-way ANOVA), indicating a role for CARD9 in a radiosensitive hematopoietic compartment." (PMID 27032818, 2016).
cardiac hypertrophy (5 papers, 2017 to 2025). "Transplantation of Card9−/− BM cells to WT mice also inhibited cardiac hypertrophy under ISO infusion compared with the control chimeric mice." (PMID 39118286, 2024). "In conclusion, we demonstrate that zinc plays a critical role in modulating the expression of BCL10 and CARD9 associated by HFD, which stimulated p38 MAPK phosphorylation and p38 MAPK‐mediated cardiac hypertrophy signalling." (PMID 28158919, 2017). "Therefore, our findings support the hypothesis that activation of BCL10/CARD9/p38 MAPK‐mediated cardiac hypertrophy pathways plays an important role in the development of ORCH." (PMID 28158919, 2017). "Furthermore, they support a model where BCL10 and CARD9 are upstream of p38 MAPK, and that their interaction directly activates p38 MAPK to promote cardiac hypertrophy." (PMID 28158919, 2017).
chronic granulomatous disease (5 papers, 2015 to 2026). Chronic granulomatous disease (CGD) is a rare primary immunodeficiency, mainly affecting phagocytes, which is characterized by an increased susceptibility to severe and recurrent bacterial and fungal infections, along with the development of granulomas. "Among the genetic disorders associated with these aspergillosis syndromes, ABPA is primarily seen with CFTR mutations, while IA and CPA are largely seen in chronic granulomatous disease (CGD), autosomal dominant hyper-IgE (Job’s) syndrome, GATA2 deficiency, and CARD9 deficiency." (PMID 36986378, 2023). "In humans, Mendelian defects in MyD88 and CARD9 signaling do not lead to the spontaneous development of aspergillosis, unlike individuals with Mendelian defects in NADPH oxidase activity (i.e. chronic granulomatous disease)." (PMID 25621893, 2015).
colon carcinoma (5 papers, 2018 to 2022). "It is worth mentioning that a study suggests that CARD9 causes the polarization of tumor-associated macrophages in colon cancer metastasis." (PMID 36443670, 2022). "Commensal C. tropicalis was found to increase myeloid-derived suppressor cell (MDSC) infiltration in CARD9 deficiency, contributing to the development of colon cancer." (PMID 36131933, 2022). "In addition to colonic cancer, CARD9 signaling has also been implicated in the inappropriate activation of renal cell carcinoma (RCC) cells." (PMID 30127791, 2018). "Other work has additionally shown that metastasis of colonic tumor cells to the liver depends on CARD9 signaling." (PMID 30127791, 2018). "High expression of CARD9 was reported in tumor-infiltrating macrophages and clinicopathologic analysis of colon cancer patients suggested that CARD9 expression was strongly correlated with tumor progression." (PMID 29352133, 2018). "Furthermore, CARD9-null mice provided evidence that CARD9 facilitated liver metastasis of colon carcinoma cells." (PMID 29352133, 2018). "The authors further demonstrated that a defect in CARD9 expression can impair the ability of dendritic cells and macrophages to kill invading commensal fungi, which can lead to the accumulation of MDSC and promote the development of colon cancer." (PMID 36131933, 2022).
Sepsis (5 papers, 2014 to 2025). Sepsis is defined as life-threatening organ dysfunction caused by a dysregulated host response to infection. "We observed that Card9−/− mice are susceptible to sepsis, accompanied by significant intestinal inflammation and intestinal barrier dysfunction." (PMID 35618701, 2022). "It is of great significance to ascertain the negative regulation of Card9 in sepsis, because excessive inflammation is the main cause of increased mortality in early sepsis." (PMID 35618701, 2022). "Importantly, the immune response of CARD9-deficient mice at lower doses may also diverge from the response reported using the acute sepsis model of candidemia." (PMID 40424070, 2025). "We found an obviously higher transcriptional levels of IL-1β and IL-18 in macrophages in Card9−/−-sepsis mice." (PMID 35618701, 2022). "Increased expressions of AST and ALT, representing worsening liver damage were noted in Card9−/−-sepsis mice compared with WT-sepsis mice." (PMID 35618701, 2022). "We observed that the phenotype of LPS-induced sepsis was exacerbated in Card9−/− mice, especially displaying more serious intestinal inflammation and gut barrier dysfunction." (PMID 35618701, 2022). "The number of infiltrating mononuclear macrophages (F4/80+CD11b+cells) in the intestinal cells was increased in Card9−/−-sepsis mice compared with WT-sepsis mice." (PMID 35618701, 2022). "But similar concentration of TNF-α and IL-6 was observed between WT-sepsis and Card9−/−-sepsis mice." (PMID 35618701, 2022). "We also observed that the expression of IL-1β (p17) and Caspase (p20) was increased in macrophages from Card9−/−-sepsis mice compared with WT-sepsis mice." (PMID 35618701, 2022). "To evaluate the function of Card9 in sepsis, we established LPS-induced sepsis in WT and Card9−/− mice." (PMID 35618701, 2022). "By using alcian blue staining, the damage of intestinal barrier was obviously aggravated in Card9−/−-sepsis mice, compared with WT-sepsis mice." (PMID 35618701, 2022). "Meanwhile, the survival rate was significantly lower of Card9−/−-sepsis mice than that of WT-sepsis mice." (PMID 35618701, 2022). "More inflammatory cells infiltration and increased destruction of intestinal mucosa structure were observed in Card9−/−-sepsis mice compared with WT-sepsis mice." (PMID 35618701, 2022). "The H&E-staining of intestines displayed the reduced lesion area and the recovery of the intestinal barrier in Ad-Ripk2 treated Card9−/−-sepsis mice compared with Card9−/−-sepsis mice." (PMID 35618701, 2022). "Taken together, these results suggest that Card9-dependent fungal recognition in the bone marrow drives myelopoiesis and the induction of immunosuppressive MDSCs that are protective against lethal inflammation and sepsis." (PMID 41170853, 2025). "In conclusion, we have characterized changes in the bone marrow compartment that are induced by C. dubliniensis, dependent on Card9 signaling, and that drive myelopoiesis and the development of MDSCs that are protective against lethal polymicrobial sepsis of intra-abdominal origin." (PMID 41170853, 2025). "Importantly, bone marrow expansion, as well as C. dubliniensis-mediated protection against sepsis, requires the C-type lectin receptor adaptor protein Card9, suggesting that fungal recognition is an important component of this process." (PMID 41170853, 2025). "Similarly, the expression of ZO-1, Occludin, Claudin-2, detected by immunohistochemistry, was increased in the intestinal tissue in Card9−/−-sepsis mice treated with Ad-Ripk2 compared with Card9−/−-sepsis mice." (PMID 35618701, 2022). "Moreover, we detected substantially decreased expression of tight junction proteins in Card9−/−-sepsis mice compared with WT-sepsis mice, including ZO-1, occludin and Claudin-2." (PMID 35618701, 2022). "In our study, we established LPS-induced sepsis model in wild-type (WT) and Card9−/− mice." (PMID 35618701, 2022).
Sepsis (continued). "However, there were no remarkable differences in creatinine and AMY protein levels between Card9−/−-sepsis and WT-sepsis mice." (PMID 35618701, 2022). "Analysis of cytokines and physiological indexes in serum revealed that pre-treating mice with Ad-Ripk2 could prevent sepsis in Card9−/−mice." (PMID 35618701, 2022). "In this study, we validated Card9 as a negative regulation factor of sepsis." (PMID 35618701, 2022). "In addition, excessive expression of NLRP3 were more obvious in macrophages from Card9−/−-sepsis mice compared with WT-sepsis mice." (PMID 35618701, 2022). "Strikingly, CARD9-deficient mice had predominantly CNS involvement, with neurological symptoms appearing late during infection and progressive brain fungal burden in the absence of fulminant sepsis, reflecting the human syndrome." (PMID 40424070, 2025). "Taken together, we suggested Card9 acts as a negative regulation factor of NLRP3 inflammasome activation, which protects against intestinal damage during sepsis." (PMID 35618701, 2022).